MYC (MYC proto-oncogene, bHLH transcription factor)
Diseases named in the same sentence as MYC in open-access papers (continued):
Sharing a sentence is not in itself a finding about the gene and the disease.
cancer (continued). "DNA replication can be deregulated by oncoproteins, such as transcription factor MYC, aberrantly activated in many human cancers." (PMID 38227944, 2024). "In AML, the nuclear m6A reader YTHDC1 promotes the formation of m6A-containing mRNA condensates, stabilizing oncogenic transcripts like MYC mRNA and promoting cancer cell survival." (PMID 39085650, 2024). "This pathway is a potential treatment target in MYC-induced cancer, in combination with other anti-cancer drugs." (PMID 37450923, 2024). "In a nutshell, MYC activation in cancer can occur through multiple mechanisms, including genetic, epistatic, epigenetic, post-translational, and direct genetic activation, which can differ among cancer types." (PMID 39164274, 2024). "Colonic cells incubated with S. gallolyticus showed elevated levels of β-catenin, c-MYC, and proliferating cell nuclear antigen (PCNA), which are transcription factors linked to cancer development." (PMID 39726700, 2024). "USP1 is an oncogene that deubiquitinates and stabilizes c-MYC, thereby promoting cancer progression in vitro and in vivo." (PMID 39513905, 2024). "c-MYC is frequently overexpressed in MDR variants, and its levels are positively correlated with the abundance of P-gp on cancer cell membranes." (PMID 37450923, 2024). "This guides us to further unravel how MYC orchestrates cancer growth by mediating metabolism and oncoimmunology." (PMID 38390324, 2024). "A pivotal aspect of our research was the elucidation of the IL-11/JAK1/STAT4/CBP signaling axis and its role in the upregulation of c-MYC, marking a significant progression in cancer biology." (PMID 38429845, 2024). "MYC activation contributes to many cancer hallmarks, including proliferation, self-renewal, cell survival, and genomic instability, all of which are associated with therapeutic resistance." (PMID 39164274, 2024). "In the context of cancer progression, MYC can induce telomerase activity, which enables bypass of the replicative senescence barrier in mammary epithelial cells." (PMID 39545637, 2024). "The MYC oncogene is activated in the majority of human cancers and has proven challenging to target therapeutically." (PMID 38302473, 2024). "MYC upregulation is associated with multidrug refractory disease and contributes to MDR in patients with cancer." (PMID 37450923, 2024). "Further, our observations also provide comprehensive insights into specific genes and pathways that confer cellular fitness in MYC-driven cancers." (PMID 38302473, 2024). "The rationale behind this lies in the fact that many cancer-related TFs, such as steroid receptors, MYC, and NF-κB, all utilize the same set of coregulators." (PMID 38564048, 2024). "While alternative strategies are still needed to target the ‘undruggable’ MYC oncogene (overexpressed in about 70% of all cancers), targeting tyrosine kinases amplified and overexpressed in specific cancers has shown some success." (PMID 38999925, 2024). "Multiple studies demonstrated that MYC plays an important role in tumorigenesis, and is regarded as an attractive target for cancer therapy 39-45." (PMID 38169606, 2024). "Estimating up to 70% of cancers are affected by MYC aberration, MYC therefore has been perceived as one of the most valuable targets for cancer therapy." (PMID 38390324, 2024). "Here, we investigate the co-amplification of MED30 and MYC across diverse cancer types and its impact on oncogenic transcriptional programs." (PMID 38766212, 2024). "All of these results support the clinical potential of LC-1-40 as a lead for cancer therapeutics against MYC(N)-driven tumors." (PMID 38493213, 2024). "The ERK, MYC, and STAT3 signaling pathways have all been implicated in the activation of EZH2 in different types of cancer, including hematopoietic malignancies." (PMID 38339397, 2024).
cancer (continued). "MXI1 is a transcriptional repressor that negatively regulates the function of MYC, the accumulation of which activates cell cycle progression and cellular transformation in several cancers." (PMID 39599858, 2024). "MYC also profoundly regulates cancer cell metabolism, mitochondrial biogenesis, and enzymes involved in glycolysis and OXPHOS." (PMID 38715059, 2024). "Injury-induced populations were highest for TFs related to cell proliferation, self-renewal, and cancer involving both intrinsic (E2F family, MYC, and ZFX) and extrinsic (HIF1a, EPAS1/HIF2a, NFYB, LEF1, GLI2, VDR, and SMAD1/3/5) pathways." (PMID 38905342, 2024). "Our results provide a strategy for treating KRAS-mutant cancers through personalized selection based on MYC expression." (PMID 38992694, 2024). "Our findings demonstrate a new mechanism by which JMJD6 coordinates metabolic programs and alternative pre-mRNA splicing, providing a rationale to target JMJD6 as a therapeutic target for MYC-driven cancers." (PMID 38488852, 2024). "KEGG enrichment analysis of CSPG4P12 co-expressed genes showed that they were mainly enriched in cancer-related pathways such as G2M, MYC, and E2F." (PMID 38808892, 2024). "Experimentally, the inhibition of MYC expression reverses tumorigenesis in transgenic mouse cancer models using tetracycline-regulated (Tet) MYC expression systems." (PMID 38302473, 2024). "Both the Na+/amino acid exchanger SLC1A5 and the unidirectional Na+/Cl-/amino acid isotropic transporter protein SLC6A14 are regulated by MYC and are often overexpressed in various types of cancer." (PMID 39051546, 2024). "We recently discovered the effectiveness of blocking small ubiquitin-like modifier (SUMO) signaling cascade (SUMOylation) in MYC-expressing KRAS-mutant cancer cells using a SUMO-activating enzyme E inhibitor TAK-981 that results in SUMOylation inhibition." (PMID 39334463, 2024). "N-MYC is expressed in neural tissue and early hematopoietic development, and is deregulated in different cancer types, in particular neuroblastoma, where it can functionally substitute for c-MYC." (PMID 39164274, 2024). "Activation of MAPK and PI3K/AKT signaling pathways, both of which are commonly dysregulated in cancer, can lead to MYC deregulation by altering MYC protein stability and accumulation." (PMID 39031286, 2024). "Inability to target the enhanced pre-mRNA splicing of metabolic genes in MYC-driven cancer cells by pharmacological inhibition of JMJD6 is another limitation, due to lack of selective and potent JMJD6 inhibitors." (PMID 38488852, 2024). "In this study, using MYC-amplified (Group 3) and non-MYC amplified MB cell lines in vitro and in vivo, we evaluated anti-cancer efficacies and molecular mechanism(s) of MP1." (PMID 38200580, 2024). "In 1982, it was reported that the translocation involved the transforming sequences of the myelocytomatosis (MYC) retrovirus MC29, being the first consistent cancer-associated translocation described." (PMID 39766110, 2024). "Deregulation of MYC expression is a widespread event in carcinogenesis and is reported to occur in nearly 70% of all cancers." (PMID 38965558, 2024). "We show here that several genes involved in mRNA processing and transport play essential roles in MYC-driven cancer cells." (PMID 38302473, 2024). "In human cancers MYC is a frequently deregulated oncogene and a ‘most wanted’ target in cancer therapy." (PMID 38321218, 2024). "MYC transcription factors are key regulators of cell growth and proliferation and are established targets for cancer therapy." (PMID 39830506, 2024). "The regulatory network of MYC is extensive, spanning across gene targets and cofactors involved in various aspects of cancer development, including cellular metabolism and immunology." (PMID 38390324, 2024). "This indicates that late-stage or recurring cancer cells, which are likely to have elevated MYC levels, must possess increased DNA damage." (PMID 39563886, 2024).
cancer (continued). "MYC itself provides a frank demonstration of the importance of increased translation to cancer mechanisms." (PMID 38202281, 2024). "Given the important role of c-MYC in cancer and leukemogenesis, we further investigated the functional relationship between CNOT3 and c-MYC." (PMID 38491013, 2024). "With its widespread deregulation and significant contribution to cancer initiation, perpetuation, and advancement, targeting MYC is a compelling approach to combat this ailment." (PMID 38469312, 2024). "Alterations in MYC expression found in various types of cancers make this oncogene an appealing therapeutic target." (PMID 39217152, 2024). "Growing evidence indicates that MYC regulates tumorigenesis through a variety of mechanisms, and is functionally involved in up to 70% of all human cancers." (PMID 38169606, 2024). "The catalytic subunit of the KAT module, GCN5/KAT2A, is an important co-activator of MYC target genes during normal mouse development and in human cancer cells." (PMID 38236941, 2024). "KEGG analysis of the upregulated proteins yielded “Pathways in cancer” and “Cell cycle” as enriched terms for c-MYC." (PMID 38166947, 2024). "MYC is deregulated in more than half ofhuman cancers and profoundlyaffects cancer formation, maintenance, and progression." (PMID 39698270, 2024). "In this review, we enumerate the recent studies that characterize the targets and partners of MYC involved in cancer metabolism and immunology." (PMID 38390324, 2024). "MYC oncogene promotes tumourigenesis by coordinating cancer cell proliferation with metabolic adaptation to the consequent excessive oxidative stress." (PMID 38493213, 2024). "The tumor suppressor PTEN and the tumor necrosis factor (TNF) were the second (degree = 54) and third (degree = 53) more connected nodes, respectively, and like MYC, they both play a role in various types of cancer." (PMID 39595075, 2024). "As a transcription factor, the proto-oncogene MYC is considered to be the main driver of various malignant tumors." (PMID 38240704, 2024). "Although several of the identified oncogenes such as MYC, ETV1, and CCND1 have been previously linked to enhancer hijacking, we identified their novel hijacked enhancers that are cancer type specific." (PMID 39033128, 2024). "Signaling pathways, including MEK-ERK1/2, pSTAT3, and MYC signaling were demonstrated to activate EZH2 transcription in different cancer types." (PMID 38339397, 2024). "Polyamine metabolism is coordinately regulated by the proto-oncogene, MYC, particularly in proliferative tissues, and is further augmented in many cancer cells harboring hyperactivated MYC51,52." (PMID 38594321, 2024). "Gene set enrichment analysis (GSEA) showed that several crucial cancer hallmark signatures were enriched in KMT2D-KO SCC23 cells, including glycolysis, mTORC1 signaling, MYC targets, and ribosome biogenesis." (PMID 39117659, 2024). "GClnc1 promotes cancer progression by partially activating MYC; MYC mRNA levels were significantly increased on GClnc1 overexpression and significantly decreased after GClnc1 silencing; hence, MYC and GClnc1 levels are positively correlated." (PMID 37450923, 2024). "The MYC oncogene family coordinates protein synthesis in MYC/N‐driven cancer cells by monopolizing the production of ribosomal components and controlling protein folding to cope with altered protein synthesis." (PMID 37975412, 2024).
cancer (continued). "In DLBCL, c-MYC has been implicated in the transcriptional activation of the lncRNAs NEAT1 and FIRRE, which facilitate cancer cell proliferation." (PMID 38886753, 2024). "In particular, the LIN28B/Let-7/MYC axis has been reported in several types of cancers, including MM." (PMID 39482742, 2024). "DNA-PKCs activates AKT/GSK3 leading to indirect stabilization of c-MYC which supports cancer cell growth and metabolism." (PMID 39043779, 2024). "Overexpression of MYC is a common feature across various cancers, particularly in aggressive subtypes such as triple-negative breast cancer." (PMID 39343006, 2024). "MYC is involved in the deregulation of most hallmarks of cancer (proliferation, differentiation, apoptosis, metabolism, immune surveillance, and angiogenesis)." (PMID 38715059, 2024). "Although studied primarily in the context of MYC overexpression in cancer, JQ1 and other BET protein inhibitors have also been employed in non-cancer settings including fibrosis and cardiac diseases." (PMID 38493137, 2024). "A crucial driver of splicing dysregulation in human cancer is the oncogenic transcription factor MYC." (PMID 38413979, 2024). "MYC is tightly regulated in non-cancer cells and quiescent cells have minimal or hardly detectable levels that increase in response to signals related to growth and development." (PMID 39457457, 2024). "KLF4 and MYC are also cohesively involved in the transcriptional regulation of stem cells, development and cancer." (PMID 38561775, 2024). "Our selection of HL60, a MYC drug-sensitive cancer cell line, served as the model system for this screening process." (PMID 38424044, 2024). "Hallmark enrichment analysis revealed that RBBP6 knockdown downregulated several signaling pathways essential for cancer progression, including MYC, TNFA-NFKB, and estrogen response signaling pathways." (PMID 38503731, 2024). "C-MYC direct-targeting PROTACs represent a potentially paradigm-shifting strategy for the treatment of MYC-driving cancers." (PMID 39500878, 2024). "MYC is a gene superfamily, whose products are mainly C-MYC with collateral N-MYC and L-MYC, and considered to be a great coordinator of cancer growth and immune escape." (PMID 39135122, 2024). "Given that MYC expression correlated with cancer progression, monitoring circulating alterations in MYC over time would offer insight into the advancement of disease." (PMID 38674385, 2024). "c-MYC, a proto-oncogene with transcription factor activity, plays a critical role in cancer progression when its expression is unregulated, especially due to mutation." (PMID 39027314, 2024). "Our research prompts that BRCA1 expression and the MYC/MYCN-RAD51 axis are pivotal determinants in the anti-cancer efficacy of BI-2536 and further proposes a novel combination therapeutic strategy for SCLC care." (PMID 39085197, 2024). "ZDHHC20 inhibits chaperone-mediated autophagy of YTHDF3 through S-palmitoylation of Cys474, which can result in abnormal accumulation of the oncogenic product MYC and thereby support the malignant phenotypes of cancer cells." (PMID 38821916, 2024). "This stabilization prevents IGF2BP2 degradation via the autophagy‐lysosome pathway, facilitating MYC‐driven glycolysis in cancer cells." (PMID 39377984, 2024). "BETA analysis predicted MYC transcription to be regulated at the epigenetic level, consistent with work in cancer cells." (PMID 39482487, 2024). "For example, pharmacological inhibition of MYC-driven GLS by CB-839 has recently shown encouraging results in suppressing various cancers in vitro and in vivo, and currently examined in a phase 1 clinical trial of solid tumors (NCT02071862)." (PMID 38390324, 2024). "Overall, this study highlights the intricate and complex nature of mitotic gene regulation in cancer cells and provides a foundation for further studies in MYC-amplified cancers." (PMID 38605297, 2024).
cancer (continued). "MiRNA host genes miR-22hg, miR-24hg, and miR-101hg appeared to be suppressed by both MYCN and MYC modulation, providing a possible mechanism for TSmiR suppression in NB and perhaps other MYC-driven cancers." (PMID 38672672, 2024). "Enhanced gene expression in human cancers can result from gene amplification or chromosome translocation, such as when the MYC gene is placed under the regulation of immunoglobulin enhancer sequences." (PMID 38827026, 2024). "The GSEA results for SIGLEC9 suggest that it is involved in processes regulated by MYC, mTOR, and E2F, pathways commonly engaged in the control of cancer cell growth and survival." (PMID 39727942, 2024). "In lung adenocarcinoma, Wnt/β‐catenin signaling, along with YTHDF1, inhibits FTO expression and subsequently enhances c‐MYC expression, thereby promoting aerobic glycolysis and malignant behavior in cancer cells." (PMID 38721006, 2024). "MYC is an oncogenic driver of many types of cancer and plays a pivotal role in regulating glycolysis, glutaminolysis, nucleotide and lipid synthesis, and ribosome and mitochondrial biogenesis." (PMID 38488852, 2024). "In this study, we demonstrated the immune-independent effects of TAK-981 and its combination with the MEK inhibitor trametinib in MYC-expressing KRAS-mutant cancers." (PMID 38992694, 2024). "Accordingly, we detected a strong correlation between NPM1 and MYC expression, which has also been reported for other cancers before." (PMID 39529166, 2024). "Taken together, these results, suggest that SUMOylation inhibition suppresses the growth of MYC-expressing KRAS-mutant cancer cells." (PMID 38992694, 2024). "JQ1 effectively inhibits the growth of various cancer cells by blocking the transcriptional programs essential for cancer progression, such as those regulated by the oncogene MYC." (PMID 39066258, 2024). "Published studies have used various approaches to investigate the complex interactions between MYC and PD-L1 expression levels, revealing different roles of various factors in mediating PD-L1 expression across a number of carcinomas." (PMID 37450923, 2024). "For example, MDR frequently occurs in carcinomas overexpressing MYC, in which MYC increases the expression levels of efflux transporter proteins, promotes drug-repressor proteins, and reduces MYC corepressor proteins." (PMID 37450923, 2024). "In a murine carcinoma model, MYC bound the PD-L1 promoter to induce its expression, resulting in increased PD-L1 protein levels." (PMID 37450923, 2024). "In this study, the rate of MYC copy number gain and amplification increased with increasing grade in pTa tumors and was highest in muscle invasive pT2-4 carcinomas where MYC copy number gain/amplification rate further increased from pT2 to pT4." (PMID 39031286, 2024). "Recent research has revealed the PEAK1 signature, which becomes elevated under conditions of moderate to severe hypoxia, correlating with heightened MYC expression and a robust Ki67-proliferation index in cancer cells." (PMID 38136890, 2023). "The ‘Yamanaka factors’ OCT3/4, SOX2, KLF4, and c-MYC (OSKM) are essential for maintaining the characteristics of cancer stem cells." (PMID 37762678, 2023). "Our results show that miR-616 suppressed cell proliferation, colony formation and migration of cancer cells through suppressing c-MYC expression." (PMID 37685841, 2023). "Overexpression or hyperactivation of the transcription factor MYC occurs in most human cancers, and previous studies have illustrated that MYC mRNA harbors m6A." (PMID 36725888, 2023). "MYC is required for fundamental cellular processes triggering proliferation, growth, differentiation, or apoptosis and also represents a major cancer driver being aberrantly activated in most human tumors." (PMID 36969025, 2023).